Y_RNA (Y RNA )
Gene: Miscellaneous RNA gene on chromosome 10 (21,481,716 to 21,481,817, forward strand). Ensembl gene ENSG00000199222.
Homologues: Orthologues: chimpanzee Y_RNA (100% identical). Paralogues in human: Y_RNA (89% identical), RNY3 (88% identical), Y_RNA (88% identical), Y_RNA (87% identical), Y_RNA (86% identical), RNY3P1 (85% identical), Y_RNA (85% identical), Y_RNA (84% identical), RNY3P14 (83% identical), Y_RNA (83% identical), Y_RNA (82% identical), RNY3P16 (81% identical), and 95 more.